SPINT2 (serine peptidase inhibitor, Kunitz type 2)
Description:
Inhibitor of HGFAC. Also inhibits plasmin, and plasma and tissue kallikrein. Inhibits serine protease activity of TMPRSS13. Inhibits serine protease activity of ST14/matriptase and PRSS8/prostasin in vitro.
Synonyms: HAI-2; HAI2; KOP; DIAR3; PB
Tractability: Antibody: UniProt places it where antibodies can reach, with high confidence; its Gene Ontology location is reachable by antibodies, with high confidence; UniProt predicts a signal peptide or a membrane-spanning region. PROTAC: ubiquitination databases record sites on it.
Gene: Protein-coding gene on chromosome 19 (38,244,035 to 38,292,615, forward strand). Ensembl gene ENSG00000167642.
Subcellular location: Cell membrane; Cytoplasm
Subcellular location (Human Protein Atlas): Golgi apparatus; Vesicles
Pathways (Reactome):
Signal Transduction: MET Receptor Activation; Signaling by MST1
Gene Ontology:
Molecular function: serine-type endopeptidase inhibitor activity; endopeptidase inhibitor activity
Biological process: negative regulation of cell motility; negative regulation of cell-cell adhesion; epithelial cell morphogenesis; establishment or maintenance of cell polarity
Cellular component: cytoplasm; Golgi apparatus; plasma membrane; extracellular region; membrane
Genetic constraint (gnomAD): Loss-of-function variants: 19 observed, 29.83 expected, observed/expected ratio (o/e) 0.64, 90% interval 0.44 to 0.94. The upper end of that interval is the gene's LOEUF score, 0.94, which puts it in group 3 of 6, group 1 being the genes least tolerant of losing a copy. Missense variants: 276 observed, 331.55 expected, observed/expected ratio (o/e) 0.83, 90% interval 0.75 to 0.92. Synonymous variants: 139 observed, 135.81 expected, observed/expected ratio (o/e) 1.02, 90% interval 0.89 to 1.18.
Homologues: Orthologues: chimpanzee SPINT2 (99% identical), macaque SPINT2 (96% identical), dog SPINT2 (77% identical), pig SPINT2 (74% identical), rabbit SPINT2 (73% identical), guinea pig SPINT2 (72% identical), mouse Spint2 (71% identical), rat Spint2 (61% identical), tropical clawed frog spint2 (37% identical), zebrafish spint2 (32% identical), Caenorhabditis elegans K12G11.6 (13% identical), Caenorhabditis elegans C02F12.5 (12% identical), and 3 more. Paralogues in human: SPINT1 (33% identical), TFPI (19% identical), WFIKKN1 (18% identical), TFPI2 (18% identical), WFIKKN2 (17% identical), AMBP (16% identical), WFDC8 (15% identical), KIAA0319L (13% identical), EPPIN (12% identical), KIAA0319 (12% identical), LRP11 (12% identical), SPINT4 (6% identical), and 1 more.
Diseases named in the same sentence as SPINT2 in open-access papers:
SPINT2 is named in the same sentence as 75 diseases in open-access papers, as found by Europe PMC text mining. Sharing a sentence is not in itself a finding about the gene and the disease. The quoted sentences say what the papers report.
breast carcinoma (23 papers, 2007 to 2025). "Meanwhile, 4,411 genes (red dots) were positively, and 6,545 genes (green dots) were negatively associated with SPINT2 in breast cancer (FDR <0.01)." (PMID 34381422, 2021). "Specifically, module I is highly activated in the six DCIS areas identified in the original study, representing the spatial expression of breast cancer markers such as SPINT2, FXYD3, and ERBB2." (PMID 40033360, 2025). "All these results indicated that SPINT1 and SPINT2 jointly regulated cell attachment and metastasis in breast cancer." (PMID 34381422, 2021). "We discovered that SPINT1 and SPINT2 have different roles and overlapping functions in breast cancer biology." (PMID 34381422, 2021). "Results showed one out of 45 datasets for SPINT1 and 12 out of 53 analyzes for SPINT2 reported mRNA upregulation in breast cancer tissues." (PMID 34381422, 2021). "Frequently, the dysfunctional placenta suffers from suboptimal perfusion and high levels of inflammatory factors, and, in previous research, SPINT2 has been shown to be regulated by hypoxia (in breast cancer cells)." (PMID 34299087, 2021). "SPINT1 and SPINT2 expression were reciprocally correlated in breast cancer, which was in accordance with reports that they were frequently co-expressed in the same cell." (PMID 34381422, 2021). "The correlation between SPINT2 expression and prognosis in breast cancer patients with different clinicopathological parameters." (PMID 34381422, 2021). "Currently, there are few studies on the expression and functions of SPINT1 and SPINT2 in breast cancer." (PMID 34381422, 2021). "The SPINT2, an inhibitor of HGF activator, was reported to have higher expression levels in early stage breast cancer and associated with a poor prognosis, consistent with our findings." (PMID 21060876, 2010). "Elevated expression of Atp1b1, Spint2, and Acly in AA women breast cancer cells were observed when the expression levels of all AA and CAU women cell lines were compared." (PMID 17472751, 2007). "Altered expression of Atp1b1, CARD 10, KLF4, Spint2, and Acly in AA breast cancer cells was observed when the overall averages of the expression levels of all AA and CAU cancer cell lines were compared." (PMID 17472751, 2007). "As HGF activator inhibitors, serine protease inhibitor, Kunitz types 1 and 2 (SPINT1 and SPINT2) have been reported to be differentially expressed in breast cancer, but their prognostic significance and functioning mechanism remain unclear." (PMID 34381422, 2021). "The mutation of SPINT2 had no impact on OS (log-rank P = 0.340) or DFS (log-rank P = 0.126) in breast cancer patients." (PMID 34381422, 2021). "The Linkedomics results showed that SPINT1 and SPINT2 were reciprocally correlated in breast cancer (Pearson correlation = 0.437, P = 2.103e−52), which was close to the correlation statistics from cBioportal (TCGA, Firehose Legacy) (Pearson correlation = 0.42, P = 4.68e−83)." (PMID 34381422, 2021). "In addition, SPINT2 may function as a tumor suppressor gene, as its mRNA levels are down-regulated in several human cancers (e.g. gliomas, colorectal cancers and liver cancer) and a deficiency in SPINT2 expression is linked with poor prognosis of breast cancer." (PMID 23110343, 2012). "This evidence suggests that the altered expression levels of CARD10, KLF4, Acly, Atp1b1, and Spint2 may be contributing factors in the higher mortality rates of AA breast cancer patients." (PMID 17472751, 2007). "Results from this study indicates that altered expression of the genes Atp1b1, CARD 10, KLF4, Spint2, and Acly may play a role in the aggressive phenotype seen in breast cancer in African American women." (PMID 17472751, 2007). "In other studies related to breast cancer, results that contradicted the results of this study were reported, and other tumor-related studies (liver, renal, gastric, cervical, prostate cancer, and medulloblastoma) showed that SPINT2 expression was downregulated." (PMID 36294892, 2022).
breast carcinoma (continued). "However, we found decreased DNA methylation of SPINT2 in breast cancer." (PMID 34381422, 2021). "Indeed, the TCGA database indicates high SPINT2 mRNA levels in pancreatic ductal adenocarcinomas and the median level of SPINT2 mRNA is high in other major cancers such as non-small cell lung cancers, colon cancers, breast cancers and prostatic cancers." (PMID 29545930, 2018). "We note significant upregulation of genes such as EFNA1, PTMA, SPINT2, and CD24, which have previously been indicated in increased tumor aggression and driving the transition to invasive forms of breast cancer." (PMID 39801521, 2025). "Although most studies involving SPINT1 or SPINT2 reported reduced expression in cancers, we observed a paradoxical upregulated expression of SPINT1/2 in breast cancer." (PMID 34381422, 2021). "Meanwhile, the elevated expression of SPINT2 was found to be correlated with a worse OS (HR = 1.17, Cox P = 3.3e−04) and RFS (HR = 1.76, Cox P = 0.013) in breast cancer." (PMID 34381422, 2021). "ST14/Prss14 is one of such genes: its expression was low in ERlow breast cancer cell lines, clustered together with CDH1 and its two inhibitors, SPINT1 and SPINT2." (PMID 27167193, 2016). "SPINT2 (Hepatocyte growth factor activation inhibitor-2, HAI-2) is capable of regulating a HGF-induced invasion of human breast cancer cells." (PMID 21347235, 2011). "COMT might act as an anti-invasive agent on ER + breast cancer also through its newly discovered interplay with MET signaling via its interacting partner, SPINT2, leading to the inhibition of this pro-tumorigenic pathway." (PMID 36690660, 2023). "In addition, discovery of a novel interaction partners including Kunitz-type protease inhibitor SPINT2, pointed to the novel mechanism of tumor suppressor role of COMT in ER dependent breast cancer through the interplay with MET signaling pathway." (PMID 36690660, 2023). "Survival of breast cancer patients with high ST14/Prss14 expression is significantly poor in estrogen receptor (ER) negative populations regardless of the ratios of ST14/Prss14 to its inhibitors, SPINT1 or SPINT2." (PMID 27167193, 2016). "SPINT2/HAI-2 has been found to be over-expressed in pancreatic cancer and ovarian cancer and has been inversely correlated with tumor progression in renal cell carcinoma and breast cancer." (PMID 17472751, 2007). "Besides, SPINT2 upregulation was correlated with unfavorable OS and RFS in breast cancer." (PMID 34381422, 2021). "Similarly, for early breast cancer, the best three k-gene discriminators are {GPR109B, PCOLCE2, PCSK5}, {PCSK5+COL10A1, FERMT2+SPINT2, MAOA+IGJ}, {COL1A1+PCSK5+TF, GPX3+COL1A1+SPINT2, GPX3+FAP+TMEM97}, and {RRM2+COL1A1+GPR109B+IGJ, RRM2+COL1A1+GPR109B+IGJ, RRM2+COL1A1+GPR109B+SPINT2}, respectively." (PMID 21060876, 2010).
prostate carcinoma (14 papers, 2017 to 2025). A carcinoma that arises from epithelial cells of the prostate gland. "Among others, SPINT2 was associated with metastatic osteosarcoma, ovarian cancer, glioma/glioblastoma, prostate cancer and non-small lung cancer, leukemia and cervical carcinoma." (PMID 32887258, 2020). "In contrast, Kunitz-type protease inhibitor 2 (SPINT2) and prostate cancer, as well as Semaphorin-3G (SEMA3G) and CRC, were shown to have distinct variants at the gene target (i.e. PPH3 > 0.8)." (PMID 38527997, 2024). "HAI-2 is also downregulated in prostate cancer; however, no apparent methylation of SPINT2 promoter has been reported." (PMID 40299447, 2025). "In addition, we also propose that SPINT2 (OR: 1.05, 95% CI 1.03–1.06), GSTP1 (OR: 0.82, 95% CI 0.74–0.90), and CTSS (OR: 0.91, 95% CI 0.88–0.95) may serve as potential therapeutic targets in prostate cancer." (PMID 37735436, 2023).
glioblastoma (9 papers, 2013 to 2025). The most malignant astrocytic tumor (WHO grade IV). "The SPINT2 gene has been proposed to act as a putative tumor suppressor in several cancer entities, including gastric cancer, glioblastoma, medulloblastoma, melanoma, and renal cell carcinoma." (PMID 31737572, 2019). "Downregulation of the SPINT2 gene by hypermethylation is reported in cancers, including glioblastoma, hepatoma, melanoma, and RCC." (PMID 29890660, 2018). "Although previous studies have reported hypermethylation of SPINT2 and its tumor-suppressive effects in glioblastoma, its role in senescence and direct regulation by DNMT1 were unknown." (PMID 40838961, 2025).
melanoma (8 papers, 2016 to 2025). A malignant, usually aggressive tumor composed of atypical, neoplastic melanocytes. "SPINT2: The epigenetic silencing of SPINT2 promoted cancer cell motility via HGF-MET pathway activation in melanoma, and β-catenin formed a complex with c-Met (HGF receptor)." (PMID 27534621, 2016). "SPINT2 upregulation was reported to decrease p-Akt levels in melanoma cells." (PMID 31164631, 2019). "SPINT2 gene promoter has been reported to be hypermethylated in various cancers, including hepatocellular carcinoma (HCC), RCC, melanoma, gastric cancer, and esophageal squamous cell carcinoma." (PMID 40299447, 2025).
gastric cancer (7 papers, 2015 to 2025). A primary or metastatic malignant neoplasm involving the stomach. "In HAI-2-low types of cancer, downregulation of HAI-2 was mediated by promoter hypermethylation of the SPINT2 gene, and recently, SPINT2 hypermethylation was reported in other cancer types, such as esophageal carcinoma and gastric cancer." (PMID 29545930, 2018). "Promoter methylation and transcriptional silencing of HAI-2/SPINT2 is significantly linked to cell differentiation and metastasis in gastric cancer." (PMID 28512631, 2017).
hepatocellular carcinoma (7 papers, 2017 to 2025). A malignant tumor that arises from hepatocytes. "We observed SPINT2 down-regulation in Hepatocellular Carcinoma (HCC), Colon Adenocarcinoma (COAD) and renal Clear Cell Carcinoma (rCCC) tumor cells." (PMID 34181691, 2021).
ovarian carcinoma (7 papers, 2007 to 2025). A malignant neoplasm originating from the surface ovarian epithelium. "We found evidence of PITX1 and ERα binding in only one fusion gene, SPINT2, indicating that the majority of the fusion genes identified in this study contribute to ovarian cancer by mechanisms other than this regulatory network." (PMID 34215221, 2021). "The predictors, LAMA4, CA11, MEDAG, NANOG, SPINT2, let-7b, miR23b, and miR29a were found to be sufficient to classify 87.5% and 100% of ovarian cancer (n = 8) and disease control (n = 10) groups, respectively." (PMID 29499737, 2018). "Based on previous studies relating to these mRNA, CA11 and MEDAG may be involved in maintaining malignant ascites microenvironment, while LAMA4, NANOG and SPINT2 activities could regulate ovarian cancer progression and metastasis." (PMID 29499737, 2018). "In contrast to LAMA4, CA11, and MEDAG, the 2 mRNAs, SPINT2 and NANOG, were found to be increased in ovarian cancer ascites compared to peritoneal fluid EVs." (PMID 29499737, 2018). "Three mRNAs, CA11, LAMA4, MEDAG, were .01–.28-fold lower expressed and two mRNA, SPINT2 and NANOG, were 3.2–5.8-fold higher expressed in ovarian cancer ascites versus peritoneal fluid EVs." (PMID 29499737, 2018).
medulloblastoma (6 papers, 2013 to 2025). A malignant, invasive embryonal neoplasm arising from the cerebellum. "JARID1B activates c-Met in cancer stem cells.c-Met and its ligand HGF/SF are involved in epigenetic dysregulation.SPINT2/HAI-2, an inhibitor of HGF/c-Met signaling, was silenced by promoter methylation in medulloblastoma." (PMID 34055785, 2021).
congenital tufting enteropathy (4 papers, 2018 to 2023). "Conversely, mutations in human SPINT2 were associated with congenital tufting enteropathy characterized by severe intestinal dysfunction with induced EpCAM cleavage and decreased claudin-7 expression that resulted in organoid rupture." (PMID 37830556, 2023). "For histopathological classification, SPINT2 mutation-related enteropathy is classified as congenital tufted enteropathy (CTE), characterized by villous atrophy and focal crowding at the villus tips due to disorganization of enterocytes." (PMID 30623107, 2019). "Mutations in SPINT2 encoding the epithelial serine protease inhibitor hepatocyte growth factor activator inhibitor-2 (HAI-2) are associated with congenital tufting enteropathy." (PMID 30623107, 2019). "Congenital tufting enteropathy (CTE) is a life-threatening intestinal disorder resulting from loss-of-function mutations in EPCAM and SPINT2." (PMID 37539662, 2023). "Mutations in the SPINT2 gene, encoding HAI-2, have recently been described in a subset of patients with congenital tufting enteropathy (CTE)." (PMID 29617460, 2018). "Highlighted Article: Cleavage-resistant EpCAM does not prevent intestinal failure in the Spint2-deficient mouse model of congenital tufting enteropathy, challenging the current model of proteolysis-driven disease progression." (PMID 37539662, 2023).
pancreatic cancer (4 papers, 2007 to 2018). "Another common example is SPINT2, a protein that is over-expressed in pancreatic cancer and participates in tumor cell invasion and metastasis." (PMID 20700505, 2010).
choanal atresia (3 papers, 2020 to 2025). Choanal atresia (CA) is a congenital anomaly of the posterior nasal airway characterized by the obstruction of one (unilateral) or both (bilateral) choanal aperture(s), with clinical manifestations ranging from acute respiratory distress to chronic nasal obstruction. "A syndromic form, characterized by symptoms such as punctate keratitis and choanal atresia, is associated with mutations in Serine Peptidase Inhibitor Kunitz Type 2 (SPINT2)." (PMID 40310351, 2025). "Patients with SPINT2-mutation have additional features, including choanal atresia and corneal erosions." (PMID 36422736, 2023). "A syndromic condition with other abnormalities such as superficial punctate keratitis and choanal atresia was ultimately related to SPINT2 mutations." (PMID 36422736, 2023). "Moreover, the syndromic form of CTE features anal and choanal atresias as well as ophthalmologic signs, which are associated with mutations in the gene encoding Serine Peptidase Inhibitor Kunitz Type 2 (SPINT2)." (PMID 33029133, 2020). "Meanwhile, the form of CTE associated with SPINT2 mutations is similar to that associated with EPCAM mutations but includes the additional symptoms of systemic keratitis and choanal atresia." (PMID 36422736, 2023).
congenital sodium diarrhea (3 papers, 2017 to 2019). Congenital sodium diarrhea is characterized by severe watery diarrhea containing high concentrations of sodium, hyponatremia and metabolic acidosis. "Choanal (CA) and gastrointestinal atresias (GA) are an important feature of syndromic congenital sodium diarrhea (sCSD), a disorder recently associated with mutations in the gene for serine protease inhibitor type 2 (SPINT2)." (PMID 29499739, 2018).
glioma (3 papers, 2012 to 2020). A benign or malignant brain and spinal cord tumor that arises from glial cells (astrocytes, oligodendrocytes, ependymal cells). "Moreover, in high-grade glioma, higher SPINT2 expression was determined to be associated with better OS." (PMID 31221203, 2019). "Regarding dysregulation of the HGF/MET signaling pathway, the SPINT2 gene has been extensively studied in gliomas." (PMID 31221203, 2019).
enteropathies (2 papers, 2019 to 2023). "Our findings provide new insights into the role of EpCAM and the etiology of the enteropathies driven by Spint2 deficiency." (PMID 37539662, 2023).
kidney carcinoma (2 papers, 2016 to 2019). Primary or metastatic malignant neoplasm involving the kidney. "Among these genes, INHBA, MT1G and SPINT2 were reported to have tumor suppressive functions in renal cancers." (PMID 26551931, 2016). "While a strong association with a short survival was also observed for AML, lung adenocarcinoma and Ewing sarcoma, the opposite was true for instance for kidney carcinoma, meningioma, metastatic melanoma and OC, suggesting that SPINT2 may not be classified as a general tumor suppressor or promoter." (PMID 31737572, 2019).
lung carcinoma (2 papers, 2019 to 2023). "MDK and SPINT2 were selected due to the observed differences in overall survival while GDF15 levels have been associated with different stages of lung cancer in patients." (PMID 38260835, 2023).